IL13RA2 (interleukin 13 receptor subunit alpha 2)
Diseases named in the same sentence as IL13RA2 in open-access papers (continued):
Sharing a sentence is not in itself a finding about the gene and the disease.
astrocytomas (9 papers, 2013 to 2023). "The expression of astrocytoma-associated antigens (IL13Rα2, Fra-1, and EphA2) in particular stages of astrocytoma-derived cultures was assessed both at the mRNA and protein levels." (PMID 25788865, 2014). "Based on previously published data, astrocytoma-associated antigens (AAAs), such as Interleukin-13 Receptor α2 (IL13Rα2), Fos-Related Antigen 1 (Fra-1), and EphA2 receptor tyrosine kinase (EphA2) were selected." (PMID 25788865, 2014). "Moreover, the original tumours were evaluated concerning astrocytoma-associated antigens expression (IL13Rα2, Fra-1 and EphA2) using the real-time PCR method." (PMID 25788865, 2014). "The purpose of our study was to estimate the value of astrocytoma-associated antigens (AAAs) - IL13Rα2, Fra-1, EphA2 - and the most common molecular aberrations typical for astrocytomas as potential markers to screen the status of tumour-derived cell cultures in vitro." (PMID 25788865, 2014). "Three astrocytoma specimens showed staining for IL-13Rα2 (1.5 + and 35% positive cells (P < 0.01) compared to normal brain), but the extent of staining and percent positive cells was lower than GBM (P < 0.001)." (PMID 30572904, 2018). "Astrocytoma specimens showed lesser extent of immunostaining for IL-13Rα2 and three AP-1 factors compared to GBM specimens." (PMID 30572904, 2018). "All canine GBMs (G) contained immunoreactive IL-13RA2 similarly to human specimens while canine astrocytomas (A) seem to express less of the receptor than the human tissue lysates." (PMID 24147065, 2013). "For example, human astrocytomas, oligodendrogliomas and meningiomas demonstrated high levels of IL-13RA2 immunoreactivity." (PMID 24147065, 2013). "Human and canine astrocytomas and oligodendrogliomas were also positive for IL-13RA2 to various degrees." (PMID 24147065, 2013). "Based on the observations presented here, a Phase I clinical trial in the treatment of canine astrocytomas has begun utilizing IL-13RA2- and EphA2- targeted cytotoxins in combination." (PMID 24147065, 2013). "Il13Rα2 receptor specific for astrocytoma cells had been previously investigated as a route to specific delivery of drugs to GB cells based on different types of nanocarriers conjugated with IL13 homing-peptide being a ligand for Il13Rα2." (PMID 37508570, 2023). "Since GBM (defined as astrocytomas WHO grade IV) displayed the highest levels of IL13Rα2 expression, we tested whether astrocytomas (WHO II and III) over-expressed IL13Rα2 more frequently than histologically distinct oligoastrocytomas or oligodendrogliomas of the same grade (WHO II and III)." (PMID 24204956, 2013). "We show that astrocytoma and GBM samples overexpress IL-13Rα2 and constitutively express AP-1 transcriptional factors." (PMID 30572904, 2018). "Analysis of 21 GBM and astrocytoma and normal brain specimens revealed that all GBM specimens overexpressed IL-13Rα2 with high degree of correlation with c-Jun, Fra-1 and c-Fos activation while Jun D and Jun B were not expressed." (PMID 30572904, 2018). "In the present study, we have examined whether IL-13 can signal through IL-13Rα2 via AP-1 pathway in GBM cell lines and in astrocytoma and GBM specimens in situ." (PMID 30572904, 2018). "Astrocytoma samples showed lower expression of Fra-1 and c-Fos but none of the normal brain specimens were positive for IL-13Rα2 and AP-1 factors." (PMID 30572904, 2018). "However, the significance of overexpression of IL-13Rα2 in GBM and astrocytoma and signaling through these receptors is not known." (PMID 30572904, 2018).
renal cell carcinoma (9 papers, 2015 to 2024). "In renal cell carcinoma cells, knockdown of IL-13Rα2 or inhibition of IL-13Rα2 with telmisartan increased FOXO3 expression and induced apoptosis of cancer cells." (PMID 39598436, 2024). "In renal cell carcinomas, IL-13Rα2 regulated cancer progression through the regulation of the JAK2/FOXO3 pathway." (PMID 39598436, 2024). "PM-RCC, a renal cell carcinoma cell line served positive control showed high mRNA expression of IL-13Rα2." (PMID 30572904, 2018). "IL13RA2 was originally cloned from the human renal cell carcinoma Caki-1 cell line." (PMID 26114873, 2015). "The outcomes of these investigations have demonstrated significant cytotoxic effects on cancer cell populations in GBM, renal cell carcinoma (RCC), and head and neck squamous cell carcinoma (HNSCC), highlighting the potential of this targeted approach in the treatment of cancers expressing IL-13Rα2." (PMID 38612592, 2024).
gastric cancer (8 papers, 2016 to 2025). A primary or metastatic malignant neoplasm involving the stomach. "In the present study, 507 gastric cancer specimens were used to show the association between IL-13Rα2 expression and overall mortality after gastrectomy." (PMID 27351230, 2016). "For instance, M2 macrophage-secreted CHI3L1 activated IL-13Rα2 expression of gastric cancer cells and advanced the metastasis." (PMID 38270646, 2024). "IL-13Rα2 expression was evaluated by tissue microarrays from 507 gastric cancer patients from two academic medical centers and statistically assessed for correlations with the clinical profiles and the prognosis of the patients with gastric cancer." (PMID 27351230, 2016). "In the study, we analyzed IL-13Rα2 expression by immunohistochemical analysis in gastric cancer clinical specimens and its correlation with clinicopathological characteristics." (PMID 27351230, 2016). "We revealed the prognostic value of IL-13Rα2 expression in gastric cancer, especially in more advanced tumors." (PMID 27351230, 2016). "The aim of this study was to investigate the impact of IL-13Rα2 expression on the prognostic value in gastric cancer patients after surgery." (PMID 27351230, 2016). "Increased IL-13Rα2 expression might be an independent prognostic factor for decreased overall survival in gastric cancer patients after surgical resection." (PMID 33804263, 2021). "Interleukin-13 receptor α2 (IL-13Rα2) plays a vital role in the invasion and metastasis of various types of cancer, but its role in prognosis of patients with gastric cancer remains unknown." (PMID 27351230, 2016). "IL-13Rα2 expression might be an independent prognostic factor for gastric cancer after surgical resection and could potentially be a high-priority therapeutic target." (PMID 27351230, 2016). "IL-13Rα2 expression was an independent prognostic indicator for gastric cancer (P < 0.001)." (PMID 27351230, 2016). "As a result, we raised hypothesis that mast cells can secret IL-13 to promote metastasis via IL-13Rα2 in gastric cancer." (PMID 27351230, 2016). "We evaluated the prognosis based on the expression of IL-13Rα2 in gastric cancer tissues." (PMID 27351230, 2016). "However, the role of the IL-13Rα2 involved in gastric cancer remains far from being understood." (PMID 27351230, 2016). "Hence, it is reasonable for us to raise the hypothesis that IL-13Rα2 plays an important role in tumor progression and metastasis in gastric cancer." (PMID 27351230, 2016). "Thus, illumination of the significance of IL-13Rα2 expression in gastric cancer might provide some additional prognostic information other than the TNM staging system for a further risk stratification and provide guidance for a more precise treatment for gastric cancer patients." (PMID 27351230, 2016).
hepatocellular carcinoma (6 papers, 2020 to 2025). A malignant tumor that arises from hepatocytes. "In hepatocellular carcinoma, elevated IL13RA2 correlated with improved patient survival, while silencing IL13RA2 had pro-proliferative, pro-survival effects analogous to those reported here, albeit via ERK activation." (PMID 40663259, 2025). "IL13RA2 knockdown confered invasive and metastatic abilities to hepatocellular carcinoma cells throng activating ERK pathway." (PMID 39220137, 2024). "Furthermore, CD3/Fn14 BiTE, CD3/B7-H3 BiTE, CD3/EGFR BiTE, and CD3/IL13Rα2 BiTE have also shown promising results in preclinical studies of glioblastoma and hepatocellular carcinoma (HCC)." (PMID 37596653, 2023). "Expression of interleukin‐13 receptor alpha 2 (IL13RA2), one of the receptors for interleukin‐13, is low in hepatocellular carcinoma (HCC) compared with normal hepatic tissue." (PMID 31823484, 2020).
liver fibrosis (6 papers, 2013 to 2025). "In addition, it was found that P-selectin, acts as a decoy-receptor up-regulating IL-13Rα2 in S. mansoni infection with subsequent exacerbation of S. mansoni associated liver fibrosis due to increased IL-13activity." (PMID 25066324, 2014). "Inhibiting IL-13 activity with IL-13Rα2 can reduce liver fibrosis." (PMID 36743413, 2023). "Elevated levels of circulating IL-13 and increased expression of IL-13 receptor alpha 2 (IL-13Rα2) in the liver have been reported in individuals with MASH, with liver fibrosis mitigation observed upon targeting IL-13Rα2+ cells, including HSCs." (PMID 40370443, 2025). "Profibrotic factors such as IL-1α and IL-1β that play a role in liver fibrosis development, and TNF-α which is an essential cofactor of IL-13 to induce the expression of IL-13Rα2, were upregulated." (PMID 24143891, 2013). "It has been reported that functional IL-13Rα2 was upregulated in activated hepatic stellate cells (HSCs) in NASH, and IL-13 cytotoxin-mediated killing of IL-13Rα2+ cells can ameliorate liver fibrosis in a rat model of NASH, indicating the involvement of the IL-13/IL-13Rα2 pathway in NASH." (PMID 36032141, 2022). "Our data indicate that HCV infection could promote IL13RA2 expression in HSC, which could be further upregulated by HIV co-infection, supporting the role of this factor in accelerated hepatic fibrosis by HCV/HIV co-infection." (PMID 30679661, 2019).
thyroid cancer (6 papers, 2019 to 2024). "IL-13Rα2 is frequently up-regulated in thyroid cancers, and IL-13Rα2-specific PEP-1 was used to increase the specific binding between NPs and ATC cells." (PMID 37833748, 2023). "IL-13Rα2 is frequently up-regulated in thyroid cancer tissues and is considered as a therapeutic target of thyroid cancer." (PMID 33457193, 2021). "This is because IL-13Rα2 is frequently up-regulated in thyroid cancers and is considered as a target protein of thyroid cancer." (PMID 33457193, 2021). "In PTC, IL13Rα2-induced cell migration is associated with the upregulation of EMT markers such as N-cadherin, Vimentin and Snail, indicating that IL13Rα2 enhances thyroid cancer aggressiveness through promoting EMT process." (PMID 32655554, 2020). "In thyroid carcinomas, EMT markers, including N-cadherin, Vimentin and Snail, are regulated by IL13RA2." (PMID 31585531, 2019). "However, the potential mechanism of how IL13Rα2 influence the EMT process of thyroid cancer is not clear." (PMID 32655554, 2020).
breast tumors (5 papers, 2010 to 2022). "Kaplan-Meier survival analysis further indicated that increased IL13Rα2 levels are associated with shorter metastasis-free survival of patients with high-grade breast tumors." (PMID 26208975, 2015). "To further support these findings, we performed a meta-analysis of gene expression microarray data from the MSKCC primary breast tumor cohort which indicated that high IL13Rα2 levels are significantly associated with the basal compared with luminal tumor subtype as well as bad prognosis." (PMID 26208975, 2015). "Collectively, these data indicated that high IL13Rα2 levels might be involved in metastatic progression of basal-like breast tumors." (PMID 26208975, 2015). "Therefore, the development of therapeutic strategies using small molecule inhibitors against Activin receptors or neutralizing antibodies targeting Activin A ligand, could be used as an alternative approach for breast tumors overexpressing INHBA and/or IL13Rα2." (PMID 30805303, 2019).
colitis (5 papers, 2018 to 2022). Inflammation of the colon. "The role of IL-13Rα2 is further supported by murine data showing a more rapid recovery of IL13RA2 KO mice compared to WT mice after DSS induced colitis, with a more rapid restoration of goblet cells." (PMID 30619339, 2018). "First, we performed experimental studies with IL13RA2 KO and WT mice subjected to experimental colitis." (PMID 30619339, 2018). "Indeed, the first in vivo results were published showing that the usage of anti-IL13Rα2 in mice during DSS-induced colitis resulted in less severe disease and shorter recovery durations." (PMID 35563847, 2022). "In support of this, recent studies have shown that IL-13 acts to mediate recovery and repair in the gut following dextran sulphate sodium (DSS)-induced colitis, which is Th1 driven, as disease was improved in both IL-13Rα2 KO mice and in mice treated with a neutralizing IL-13Rα2 antibody." (PMID 34078488, 2021). "IL-13Rα2 knockout mice were protected from the induction of colitis in a DSS induced colitis model." (PMID 34737752, 2021). "Acute colitis was induced in IL13RA2 KO and WT mice by DSS administration." (PMID 30619339, 2018). "However, we did not notice any difference in macro- or microscopic inflammation between WT and IL13RA2 KO mice in this acute DSS colitis model, arguing against a role for IL13RA2 in the inflammatory process." (PMID 30619339, 2018). "This was confirmed by IL-13Rα2 antibody mediated neutralization in 8-12-week-old BALB/c mice which showed significant amelioration in colon health, based on colon pathology score and colon length, compared to wild type (wt) mice after DSS induced colitis." (PMID 34737752, 2021). "However, a previous report demonstrated that IL-13Rα2 knock out mice were not protected from colitis development, but recovered and restored the mucosal layer faster." (PMID 34737752, 2021).
diffuse intrinsic pontine glioma (5 papers, 2021 to 2025). A neuroglial tumor that arises from the middle portion of the brain stem. "An anti-IL13Rα2 ADC was found to exert potent cytotoxic effects in IL13Rα2-positive diffuse intrinsic pontine glioma cell models and in vivo tumor models, with drug activity correlating strongly with IL13Rα2 expression levels." (PMID 40918539, 2025). "Interestingly, conjugation of another IL-13Rα2 mAb to auristatin did not impact growth of certain IL-13Rα2-expressing diffuse intrinsic pontine glioma (DIPG) cell lines, suggesting selection of appropriate drug conjugates is critical for efficacy in different tumor settings." (PMID 35464460, 2022).
fibrosis (5 papers, 2008 to 2019). the formation of excess fibrous connective tissue in an organ or tissue in a reparative or reactive process. "Of the 16 samples analysed for IL13RA2 by TaqMan real-time PCR, nine (56%) showed overexpression compared to 7/7 (100%) overexpression determined by human fibrosis PCR array." (PMID 25879570, 2015). "Fibrosis severity correlates with IL-13 levels and is reduced by expression of the IL-13 decoy receptor, IL-13Rα2, or by neutralising antibodies for IL-13 in a murine model of S. mansoni." (PMID 23840855, 2013). "Fibroblasts are also important producers of the soluble IL-13Rα2, which can function as a decoy receptor for IL-13 and was recently shown to inhibit the development of fibrosis in schistosomiasis." (PMID 18369473, 2008). "Further, we hypothesized that TGF-β1 stimulated by IL-13 signaling through IL-13Rα2 is responsible for this allograft fibrosis and that blockage of the pathway by IL-13Rα2-specific siRNA can ameliorate allograft fibrosis." (PMID 24143891, 2013).
metastatic colorectal cancer (5 papers, 2017 to 2023). "The first peptide, which is derived from the D1 domain of IL-13Rα2, has been shown to exhibit therapeutic activity against metastatic colorectal cancer by competitively inhibiting IL-13 binding to IL-13Rα2 and thereby the receptor signaling." (PMID 37345109, 2023). "Since no clinical trials have been developed for targeting IL13Rα2 in metastatic colorectal cancer, we propose a novel strategy based on blocking the IL-13/IL13Rα2 signalling axis with IL13Rα2 peptides to inhibit their prometastatic functions." (PMID 30318506, 2018). "Interleukin 13 receptor α2 (IL13Rα2) is overexpressed in metastatic colorectal cancer." (PMID 30318506, 2018).